IL33 (interleukin 33)
Diseases named in the same sentence as IL33 in open-access papers (continued):
Sharing a sentence is not in itself a finding about the gene and the disease.
heart failure (55 papers, 2011 to 2026). Inability of the heart to pump blood at an adequate rate to meet tissue metabolic requirements. "A great quantity of soluble ST2 is produced during myocardial damage, making the heart lack enough IL-33 protection, which causes the heart to bear sustained pressure, cell death, and tissue fibrosis, resulting in heart function damage and even heart failure." (PMID 34659832, 2021). "sST2 is associated with increased risk of death, heart failure or ventricular arrhythmia, as it reduces protective impact of IL-33 on myocardium." (PMID 32222805, 2020). "The finding that IL-33 is cardioprotective has led to classifying the IL-33 inhibitor sIL-1R4 as a biomarker of cardiac stress and a risk factor for heart failure." (PMID 30541566, 2018). "IL-33 inhibits cardiac hypertrophy caused by AngII through activating NF-κB, and as a decoy receptor of IL-33, the serum expression of sST2 increases in patients with myocardial hypertrophy and heart failure caused by it, and the expression was correlated with the grade of heart failure." (PMID 33344656, 2020). "Serum levels of IL-33 and sST2 are increased and correlate positively with the degree of heart failure, making them potentially useful for predicting disease severity or mortality outcomes in patients with cardiovascular diseases, probably as independent risk factors of heart failure." (PMID 36291105, 2022). "The IL‐33/ST2 pathway is upregulated during heart failure, and this effect is increased under stress conditions." (PMID 40849678, 2025). "The study on a cohort of 191 people with advanced systolic congestive heart failure found IL-33's antioxidant effects on heart failure patients." (PMID 39844544, 2025). "Owing to the potentially important role of the IL‐33/ST2L axis in heart failure, we examined this axis with respect to pyroptosis." (PMID 40849678, 2025). "The ST2/IL-33 pathway is involved in many cardiovascular diseases, including ischemic and valvular heart disease, myocardial infarction (MI), heart failure (HF), myocarditis and cardiomyopathies." (PMID 37371771, 2023). "Soluble ST2 (sST2), which negatively regulates IL-33 signaling, is an established biomarker in coronary artery disease and heart failure." (PMID 37240352, 2023). "The involvement of the IL-33/ST-2 axis has been reported in various cardiovascular diseases, like coronary artery disease, atrial fibrillation, heart failure, systemic hypertension, etc.." (PMID 36552551, 2022). "The 2017 American College of Cardiology/American Heart Association Guideline for the Management of Heart Failure recommends measuring levels of cTn I, NT-proBNP and ST2/IL-33 when anticipating cardiac involvement and possible HF." (PMID 36612202, 2022). "Clinically, serum IL-33 levels are elevated in patients with cardiac failure and stent restenosis after myocardial infarction." (PMID 36337880, 2022). "Serum levels of cytokines interleukin 1 beta ( IL-1β) and interleukin 33 (IL-33) are highly abnormal in heart failure and remain elevated after mechanical circulatory support (MCS)." (PMID 34768376, 2021). "Since ventricular remodeling is often involved in various kinds of heart failure, the modulating role of sST2 in the IL-33/ST2L signaling pathway reflects its potential value as a biomarker for heart failure." (PMID 34712771, 2021). "It is elevated in heart failure, acting as a decoy receptor of IL-33 to alleviate the cardioprotective effects of IL-33." (PMID 34681575, 2021). "sST2 is elevated in heart failure patients and acts as decoy receptor of IL-33 to alleviate cardio-protective effects of IL-3312,13." (PMID 31434944, 2019). "Diagnostic and treatment algorithms incorporated predictive values of Galectin-3 (Gal-3) and interleukin-33 (IL-33) in treatment of coronary diseases and heart failure and evaluating prediabetic state." (PMID 29988422, 2018).
heart failure (continued). "This study aimed to assess the association between the IL-33/ST2 pathway and histologically determined myocardial fibrosis in heart failure." (PMID 29285671, 2018). "While increased levels of ST2 are recognized as a marker of poor prognosis in patients with myocardial infarction and heart failure, the prognostic value of circulating IL33 levels in CVD has been less clear." (PMID 26544186, 2015). "Although increased levels of the soluble receptor for IL-33, sST2, is a marker of poor prognosis in patients with heart failure and myocardial infarction, the prognostic value of circulating IL-33 in cardiovascular disease was not studied extensively." (PMID 24725541, 2014). "ST2 is a receptor for interleukin-33 and its soluble form, which is released from the myocardium and vascular endothelial cells in response to pressure or volume overload, had been proposed as a promising biomarker for heart failure." (PMID 35998199, 2022). "However, clinically, serum IL-33 levels are elevated in patients with cardiac failure and stent restenosis after myocardial infarction." (PMID 36337880, 2022). "However, it must be noted other individual studies (not included in this meta-analysis after considering inclusion/exclusion criteria) have shown different results, with IL-33 levels being higher in heart failure patients compared with controls." (PMID 34723980, 2021). "Thus, increased levels of the soluble receptor for IL-33, sST2, are recognized as a marker of poor prognosis in patients with myocardial infarction and heart failure." (PMID 24751794, 2014). "If such a mechanism is also operative in cardiac cells, one might speculate that IL-33 might also play a pathophysiological role in cardiovascular diseases such as heart failure characterized by mechanical strain impacting on the cardiac tissue." (PMID 23567618, 2013). "Nevertheless, studies on cardiomyocytes demonstrated that IL-33 might increase the activity of antioxidant enzymes and decrease oxidative stress; however, sST2 prevented this effect, indicating a complicated interplay between these biomarkers in heart failure." (PMID 39844544, 2025). "Interaction between interleukin -33 (IL-33), the transmembrane ST2 receptor (ST2L), and sST-2 plays a significant role in the inflammatory response to cardiac stress, and sST-2 is strongly associated with myocardial fibrosis, remodeling, and heart failure progression." (PMID 40564142, 2025). "IL-33/ST2 signaling pathway known for its roles in immune response and tissue repair, participates in cardiac protection and anti-cardiac fibrosis in heart failure." (PMID 40535153, 2025). "The IL-33/ST2 pathway is involved in many cardiovascular diseases, including ischemic and valvular heart disease, myocardial infarction, heart failure, myocarditis, and cardiomyopathies." (PMID 40535153, 2025). "In contrast to the known pro-inflammatory functions of IL-33, IL-33/ST2 signaling protected animals from experimentally induced cardiac failure by antagonizing angiotensin II-induced cardiomyocyte hypertrophy." (PMID 35844571, 2022). "Background: we aimed at investigating the influence of weightlessness and hypergravity by means of parabolic flight on the levels of the heart failure biomarkers H-FABP, sST2, IL-33, GDF-15, suPAR and Fetuin-A." (PMID 32423045, 2020). "Components of the IL-33/ST2 system were shown to be expressed in normal and pressure overloaded human myocardium, and soluble ST2 (sST2) has emerged as a prognostic biomarker in myocardial infarction and heart failure." (PMID 23567618, 2013). "Whereas IL-33 has been demonstrated to exert anti-inflammatory and protective effects, circulating soluble ST2 (sST2) has emerged as a prognostic biomarker in patients with myocardial infarction and heart failure." (PMID 24265755, 2013).
heart failure (continued). "Several studies have established the prognostic role of sST2 levels in myocardial infarction, heart failure, right ventricle function and dyspneic states, while there are no available data about IL-33 levels in cardiovascular disorders." (PMID 22104207, 2011). "Consequently, sST2 release dampens the beneficial IL-33/ST2L axis, shifts the immune response from a Th2 (anti-inflammatory) to a Th1 (proinflammatory) profile, and promotes cell death, fibrosis, and progression of heart failure." (PMID 40305342, 2025). "Many molecules like troponins, brain natriuretic protein (BNP), ST2/IL-33, C-reactive protein (CRP), TNF, IL-1β, and IL-18 cytokines have been already examined as molecular markers for diagnosing or predicting different cardiac disturbances like myocardial infarction, heart failure, or myocarditis." (PMID 33172097, 2020). "In HF patients this homeostatic balance between synthesis, relapse, and function of ST2 is lost, and the IL-33/ ST2 system is up-regulated in cardiomyocytes, and fibroblasts in response to acute cardiac injury, and during chronic adaptive condition of pump failure such as heart failure." (PMID 29997521, 2018).
colon carcinoma (54 papers, 2017 to 2025). "This study investigates the serum expression levels of interleukins IL-8, IL-17A, and IL-33 in patients with colon cancer, analyzing their association with tumor grade and depth of invasion." (PMID 40725273, 2025). "This study revealed the associations between serum levels of IL8, IL17A, and IL33 and colon cancer stages, as well as the correlations between these interleukins in healthy and cancer groups." (PMID 38398137, 2024). "In the mouse CT26 colon carcinoma model, systemic treatment of mice with Irinotecan induced intestinal mucositis in association with inducible IL-33 expression and enhanced neutrophil accumulation in the intestine." (PMID 34209038, 2021). "This new knowledge emphasizes the relevance of inflammatory molecules involved in UC cancer progression; however, more studies are necessary to understand the implications of miR-378 and IL-33 in colon cancer risk for UC patients." (PMID 31824476, 2019). "In a mouse model of ectopic CT26 colon carcinoma, systemic chemotherapy with irinotecan induced intestinal mucositis, associated with the induction of IL-33, and increased neutrophil accumulation in the intestine." (PMID 30483263, 2018). "In SW620 human colon cancer cells, IL-33 overexpression promoted tumor growth and migration in vitro, and tumor lung metastasis in vivo, while inhibiting IL-33 did the opposite." (PMID 39925809, 2025). "Consistently, IL-33 has been shown to promote stemness and prevent chemotherapy-induced tumor apoptosis in colon cancer, myeloid leukemia, and glioma models." (PMID 40216748, 2025). "Supporting these data, studies involving HNSCC, pancreatic carcinoma and colon carcinoma cell lines suggest that IL-33 is an autocrine/paracrine mediator of carcinoma cell invasiveness and metastasis." (PMID 38662248, 2024). "The levels of IL8 and IL33 are elevated in the early stages of colon cancer, with the highest values observed in stage 1 and stage 2, respectively." (PMID 38398137, 2024). "The association between IL8 and 17A in colon cancer has already been investigated, but the role of IL33 in colon cancer still needs to be determined." (PMID 38398137, 2024). "This study aimed to evaluate the serum levels of IL8, IL17A, and IL33 and their correlations with different stages of colon cancer." (PMID 38398137, 2024). "In our study, IL8 and IL17A were found to be higher in the cancer group, while IL33 concentration was higher in the control group, reinforcing the fact that inflammatory cytokines and colon cancer are correlated." (PMID 38398137, 2024). "This research investigated the serum levels of three interleukins (IL8, IL17A, and IL33) and the possible relationships between them in healthy people and colon cancer patients at different stages." (PMID 38398137, 2024). "The main purpose of this study was to evaluate serum concentration of IL8, 17A, and IL33 and to establish correlations among these interleukins in different stages of colon cancer." (PMID 38398137, 2024). "provided evidence showing that the activation of JNK and recruitment of macrophages by IL33 contribute to the promotion of stemness in colon cancer cells." (PMID 38923705, 2024). "The highest concentration of IL17A and IL33 was in the 60–69 age group of colon cancer subjects, with significant difference in these IL concentrations between the 60–69 age group and the other age groups." (PMID 38398137, 2024). "Owing to the complexity of the original TME, a murine CT26 colon cancer model was established in immunocompetent BALB/c mice to further assess the effect of IL-33 treatment on 5-FU chemotherapy." (PMID 37056569, 2023). "Although IL-33 administration increased the infiltration of M2-like macrophages in the CT26 colon cancer model in the present study, it led to a significant increase in T cell infiltration and tumor regression." (PMID 37056569, 2023).
colon carcinoma (continued). "Recent studies show that increased IL-33 expression in colon cancer cells promotes PPARγ expression in ILC2s, leading to IL-13 release and facilitating tumor migration." (PMID 37686309, 2023). "While IL33 can dually target tumor cells and macrophages to promote stem cell production in colon cancer to drive tumor progression." (PMID 37600653, 2023). "IL-33 recruited macrophages into the cancer microenvironment and stimulated them to produce prostaglandin E2, which supported colon-cancer stemness and tumor growth." (PMID 35382168, 2022). "Overexpression of IL-33 by colon cancer cells induces macrophage recruitment and stimulates them to produce PGE2, thereby supporting the stemness of colon cancer cells." (PMID 35740975, 2022). "IL-33 has been proved to promote colon-cancer-cell stemness via the c-Jun N-terminal kinase (JNK) activation and macrophage recruitment." (PMID 35382168, 2022). "Along these lines, recent studies investigating the role of IL-33/ST2 in colon cancer have reported contrasting results." (PMID 34071419, 2021). "Human colon cancer cell line HT-29 cells was selected and stimulated by IL-33 to up regulate IRAK1 protein expression." (PMID 33906562, 2021). "In fact, IL-33 can suppress murine colon cancer growth and metastasis by upregulating CD40L and promoting IFNγ production." (PMID 34638950, 2021). "Accordingly, IL-33 administration to CT-26 (murine colon carcinoma cell line) tumor-bearing mice promotes an increase in the ST2+ Treg population, which, through the production of Th2 cytokines, promotes cancer development." (PMID 33371444, 2020). "In a colon carcinoma model, endogenous IL-33 promoted IFN-γ expression by both CD4+ and CD8+ T cells, increased CD8+ T cell infiltration over Treg cells and augmented CD8+ T cell-mediated antitumor responses." (PMID 33329534, 2020). "Colon cancer transfection with IL-33 promotes tumour metastasis by accumulating myeloid-derived suppressor cells (MDSCs) to regulate the tumour microenvironment (TME)." (PMID 33308251, 2020). "In cancer, IL33/ST2 signaling in Tregs seems particularly important in colon cancer, where the frequency of ST2-expressing Tregs is higher and ST2-expression is upregulated compared to normal colon tissue." (PMID 32719677, 2020). "We previously demonstrated that colon cancer cell-derived sST2 suppresses tumor growth by inhibiting the Th2 response, M2 macrophage polarization and tumor angiogenesis triggered by IL-33 in the tumor microenvironment." (PMID 32340025, 2020). "In the classic carcinogen-induced mouse model of sporadic colon cancer (6x AOM), colon tumors displayed increased expression of IL33 and ST2." (PMID 32719677, 2020). "Study indicated that IL-33 promoted colon cancer cell stemness via JNK activation and macrophage recruitment." (PMID 32003751, 2020). "IL-33 promotes tumorsphere formation and prevents chemotherapy-induced apoptosis of colon cancer cells." (PMID 30691509, 2019). "The role of IL-33 in colitis as well as in colon cancer is controversial, being very dependent on the timing of alarmin activation or expression relative to the damaging insult." (PMID 30405626, 2018). "Consistently, overexpression of IL-33 in SW620 human colon cancer cells increased tumor growth, migration, and colony formation in vitro and enhanced tumor growth and lung metastasis in vivo, while inhibition of IL-33 had the opposite effect." (PMID 30205617, 2018). "Regarding the colon cancer, on the one hand, it has been supported that IL-33 promotes an IFN-γ-mediated immune protective mechanism that helps guard against the development of sporadic colon cancer that links to inflammation." (PMID 30405626, 2018). "And another study shows that overexpression of mouse IL-33 promotes colon cancer cell “stemness” and growth in vivo." (PMID 29499051, 2018). "Of note, IL-33 stimulated macrophages to produce prostaglandin E2, which supported colon cancer stemness." (PMID 30483263, 2018).